CARNS1 (carnosine synthase 1)
Description:
Catalyzes the synthesis of carnosine and homocarnosine. Carnosine is synthesized more efficiently than homocarnosine.
Synonyms: ATPGD1; KIAA1394
Tractability: PROTAC: its protein half-life has been measured.
Gene: Protein-coding gene on chromosome 11 (67,414,968 to 67,425,613, forward strand). Ensembl gene ENSG00000172508.
Subcellular location (Human Protein Atlas): Mitochondria
Pathways (Reactome):
Metabolism: Histidine catabolism
Gene Ontology:
Molecular function: ATP hydrolysis activity; carnosine synthase activity; homocarnosine synthase activity; ATP binding; metal ion binding
Biological process: carnosine biosynthetic process; L-histidine catabolic process
Cellular component: cytosol
Genetic constraint (gnomAD): Loss-of-function variants: 61 observed, 54.55 expected, observed/expected ratio (o/e) 1.12, 90% interval 0.91 to 1.38. The upper end of that interval is the gene's LOEUF score, 1.38, which puts it in group 5 of 6, group 1 being the genes least tolerant of losing a copy. Missense variants: 1,278 observed, 1,078 expected, observed/expected ratio (o/e) 1.19, 90% interval 1.13 to 1.24. Synonymous variants: 568 observed, 486.07 expected, observed/expected ratio (o/e) 1.17, 90% interval 1.09 to 1.25.
Homologues: Orthologues: chimpanzee CARNS1 (99% identical), macaque CARNS1 (98% identical), guinea pig CARNS1 (91% identical), dog CARNS1 (91% identical), pig CARNS1 (90% identical), rat Carns1 (84% identical), mouse Carns1 (84% identical). Paralogues in human: HAO1 (10% identical), HAO2 (8% identical).
Diseases named in the same sentence as CARNS1 in open-access papers:
CARNS1 is named in the same sentence as 18 diseases in open-access papers, as found by Europe PMC text mining. Sharing a sentence is not in itself a finding about the gene and the disease. The quoted sentences say what the papers report.
ischemia (3 papers, 2019 to 2022). A hypoperfusion of the BLOOD through an organ or tissue caused by a PATHOLOGIC CONSTRICTION or obstruction of its BLOOD VESSELS, or an absence of BLOOD CIRCULATION. "When ATPGD1-transgenic mice overexpressing CARNS1 were exposed to myocardial ischemia, an increase in endogenous carnosine attenuated ischemia/reperfusion-induced changes in intracellular pH." (PMID 35689661, 2022).
breast carcinoma (2 papers, 2011 to 2023). "Li Zhang and Yan Zhang indicated that CARNS1 is remarkably downregulated in breast cancer." (PMID 36914737, 2023). "Additionally, experimental data suggested that CARNS1 protein and CARNS1 mRNA levels were significantly downregulated in breast cancer." (PMID 36914737, 2023).
Alzheimer disease (1 paper, 2020). A progressive, neurodegenerative disease characterized by loss of function and death of nerve cells in several areas of the brain leading to loss of cognitive function such as memory and language. "Region S8 was shared between autism and Alzheimer disease, and within region S8, the carnosine synthase 1 gene (CARNS1) was highly expressed in brain." (PMID 32223758, 2020).
atherosclerosis (1 paper, 2022). A disease characterized by the build-up of fatty material and calcium deposition in the arterial wall resulting in partial or complete occlusion of the arterial lumen. "In short, CARNS1 and its product carnosine may play roles in diseases characterized by elevated oxidative stress and inflammatory response, such as atherosclerosis." (PMID 35837598, 2022).
clear cell renal cell carcinoma (1 paper, 2023). "Furthermore, CARNS1, which can also be an intermediate product of gout, may act as a candidate biomarker for the diagnosis and prognosis of clear cell renal cell carcinoma." (PMID 36914737, 2023).
diabetes (1 paper, 2022). "Spearman correlation analysis between their expression and clinical parameters showed that S1PR5 was associated with diabetes, heart rate, TG, TC, LDL-C, ApoB, and fasting blood glucose, while CARNS1 was associated with uric acid, suggesting S1PR5 and CARNS1 may be related to CHD." (PMID 35837598, 2022). "Diabetes, TG, TC, LDL-C, ApoB, and UA are CHD-related metabolism indicators, suggesting S1PR5 and CARNS1 may be related to the pathogenesis of CHD." (PMID 35837598, 2022). "In the patient group, S1PR5 was correlated with diabetes, heart rate, triglycerides (TG), total cholesterol (TC), low-density lipoprotein cholesterol (LDL-C), apolipoprotein B (ApoB), and fasting blood glucose (P < 0.05); CARNS1 was correlated with uric acid (UA) (P < 0.05)." (PMID 35837598, 2022).
experimental autoimmune encephalomyelitis (1 paper, 2024). An autoimmune demyelinating disease of the central nervous system that is produced experimentally in animals by the injection of homogenized brain or spinal cord in Freund's adjuvant. "Spaas and colleagues further showed that Carns1 deficiency exacerbated neuroinflammation and acrolein (a lipid-derived reactive carbonyl) in the experimental autoimmune encephalomyelitis (EAE) MS mouse model." (PMID 39234409, 2024).
lung carcinoma (1 paper, 2025). "To explore the role of CARNS1 expression in cancer malignancy, we used public databases to analyze its association with lung cancer prognosis." (PMID 41365579, 2025). "CARNS1 expression was further evaluated in publicly available lung cancer datasets, including both cell line and clinical tumor cohorts, to determine its association with patient prognosis and its correlation with HPRT1 expression." (PMID 41365579, 2025). "High CARNS1 expression was correlated with improved survival in patients with lung cancer." (PMID 41365579, 2025). "Furthermore, analysis of clinical databases showed that high CARNS1 expression correlated with improved prognosis in patients with lung cancer and negatively correlated with HPRT1 expression in tumor tissues." (PMID 41365579, 2025). "We also investigated the relationship between HPRT1 and CARNS1 expression using CCLE (lung cancer cell lines cultured in 2D) and TCGA (clinical lung cancer tissues) databases." (PMID 41365579, 2025).
osteosarcoma (1 paper, 2023). A usually aggressive malignant bone-forming mesenchymal neoplasm, predominantly affecting adolescents and young adults. "The results showed that 79 DEGs affected the prognosis of osteosarcoma, with PDE4C, CFAP44, CARNS1, GREB1L, ROF207 identified as significant risk factors and GBP1, MSC, GBP3, F13A1, CCL2 as substantial protective factors." (PMID 37796192, 2023).
pancreatic cancer (1 paper, 2023). "Model 3 primarily includes CARNS1, CNDP1, GATM, and ABAT, which are mainly distributed in tumors, particularly pancreatic cancer and breast cancer." (PMID 36914737, 2023).
tumor (3 papers, 2011 to 2025). "Carnosine inhibits tumor growth in vivo, and increased CARNS1 expression indicates enhanced carnosine production and antitumor effects." (PMID 41365579, 2025). "CARNS1 expression is closely related to tumor molecular and histological type T and M stages and survival status." (PMID 36914737, 2023). "Moreover, HPRT1 and CARNS1 expression levels were negatively correlated in clinical tumor samples, whereas no such correlation was observed in 2D‐cultured cell lines." (PMID 41365579, 2025).
cancer (2 papers, 2011 to 2025). A tumor composed of atypical neoplastic, often pleomorphic cells that invade other tissues. "Thus, our results suggest that CARNS1 could potentially represent a Maspin-dependent tumor suppressor enzyme in Claudin-low carcinomas." (PMID 21931769, 2011).
CARNS1 also shares sentences with these, for which no sentence is quoted: Coronary Heart Disease (2 papers); autism (1); gout (1); myocardial ischemia (1); type II diabetes (1); virus infection (1).